RNU6-616P (RNA, U6 small nuclear 616, pseudogene)
Gene: Small nuclear RNA gene on chromosome X (134,918,310 to 134,918,416, reverse strand). Ensembl gene ENSG00000207081.
Homologues: Orthologues: chimpanzee U6 (98% identical), macaque U6 (96% identical), pig U6 (90% identical), guinea pig U6 (87% identical), rabbit U6 (86% identical), guinea pig U6 (81% identical), dog U6 (79% identical), guinea pig U6 (71% identical). Paralogues in human: RNU6-1145P (92% identical), RNU6-38P (92% identical), RNU6-639P (90% identical), RNU6-1005P (89% identical), RNU6-1316P (89% identical), RNU6-15P (89% identical), RNU6-16P (89% identical), RNU6-20P (89% identical), RNU6-393P (89% identical), RNU6-477P (89% identical), RNU6-480P (89% identical), RNU6-1 (88% identical), and 1287 more.